OSBPL8 (oxysterol binding protein like 8)
Description:
Lipid transporter involved in lipid countertransport between the endoplasmic reticulum and the plasma membrane: specifically exchanges phosphatidylserine with phosphatidylinositol 4-phosphate (PI4P), delivering phosphatidylserine to the plasma membrane in exchange for PI4P, which is degraded by the SAC1/SACM1L phosphatase in the endoplasmic reticulum. Binds phosphatidylserine and PI4P in a mutually exclusive manner. Binds oxysterol, 25-hydroxycholesterol and cholesterol.
Synonyms: ORP8; OSBP10; MST120; MSTP120
Tractability: Small molecule: a structure with a bound ligand is known. Antibody: UniProt predicts a signal peptide or a membrane-spanning region. PROTAC: ubiquitination databases record sites on it; its protein half-life has been measured.
Gene: Protein-coding gene on chromosome 12 (76,351,797 to 76,559,809, reverse strand). Ensembl gene ENSG00000091039.
Subcellular location: Endoplasmic reticulum membrane (Isoform 1); Nucleus membrane; Endoplasmic reticulum membrane (Isoform 3)
Subcellular location (Human Protein Atlas): Cytosol; Vesicles
Pathways (Reactome):
Metabolism: Acyl chain remodelling of PS
Gene Ontology:
Molecular function: cholesterol binding; phosphatidylinositol-4-phosphate binding; phosphatidylserine binding; phosphatidylserine transfer activity; phosphatidylserine-phosphatidylinositol-4-phosphate exchange activity; protein binding; phospholipid transfer activity; lipid binding
Biological process: fat cell differentiation; intermembrane phospholipid transfer; phospholipid transport; triglyceride homeostasis; phosphatidylserine acyl-chain remodeling; positive regulation of D-glucose import; positive regulation of phosphatidylinositol 3-kinase/protein kinase B signal transduction; positive regulation of insulin receptor signaling pathway
Cellular component: endoplasmic reticulum membrane; endoplasmic reticulum-plasma membrane contact site; membrane; nuclear membrane; cytosol; endomembrane system
Genetic constraint (gnomAD): Loss-of-function variants: 32 observed, 71.97 expected, observed/expected ratio (o/e) 0.44, 90% interval 0.34 to 0.6. The upper end of that interval is the gene's LOEUF score, 0.6, which puts it in group 2 of 6, group 1 being the genes least tolerant of losing a copy. Missense variants: 562 observed, 784.2 expected, observed/expected ratio (o/e) 0.72, 90% interval 0.67 to 0.77. Synonymous variants: 237 observed, 258.65 expected, observed/expected ratio (o/e) 0.92, 90% interval 0.82 to 1.02.
Homologues: Orthologues: chimpanzee OSBPL8 (100% identical), macaque OSBPL8 (99% identical), pig OSBPL8 (97% identical), dog OSBPL8 (97% identical), guinea pig OSBPL8 (96% identical), rabbit OSBPL8 (96% identical), mouse Osbpl8 (96% identical), rat Osbpl8 (95% identical), tropical clawed frog osbpl8 (81% identical), zebrafish OSBPL8 (53% identical), Drosophila melanogaster CG3860 (13% identical), Caenorhabditis elegans obr-2 (11% identical). Paralogues in human: OSBPL5 (55% identical), OSBPL10 (21% identical), OSBPL11 (19% identical), OSBPL6 (19% identical), OSBPL1A (19% identical), OSBPL9 (19% identical), OSBP2 (17% identical), OSBPL3 (17% identical), OSBPL7 (17% identical), OSBP (16% identical), OSBPL2 (13% identical).
Diseases named in the same sentence as OSBPL8 in open-access papers:
OSBPL8 is named in the same sentence as 22 diseases in open-access papers, as found by Europe PMC text mining. Sharing a sentence is not in itself a finding about the gene and the disease. The quoted sentences say what the papers report.
hepatoma (4 papers, 2011 to 2016). "To assess a putative role of ORP8 in the production and lipidation of nascent HDL produced by hepatocytes, we employed the mouse hepatoma cell line Hepa1-6, which was subjected to shRNA-mediated silencing of Osbpl8." (PMID 23554939, 2013).
Obesity (4 papers, 2013 to 2022). Accumulation of substantial excess body fat. "Interestingly, Osbpl8 was recently found to be target of miR-143, a micro-RNA induced in the liver in genetic and dietary mouse models of obesity, and the hepatic ORP8 protein was shown to be down-regulated under these conditions." (PMID 23554939, 2013).
pancreatic cancer (4 papers, 2019 to 2023). "Such as CMSS1 and ZHX2 in uterine cancer, OSBPL8, FAM214A in breast cancer, TPT1, GPRIN3, and VAV3 in pancreatic cancer." (PMID 37024957, 2023). "The data demonstrated that OSBPL3, OSBPL8, OSBPL10, and OSBPL11 were overexpressed in pancreatic cancer tissues." (PMID 34829830, 2021).
liver cancer (3 papers, 2021 to 2023). An epithelial or non-epithelial malignant neoplasm that arises from the liver. "The mRNA of OSBPL2, OSBPL3, and OSBPL8 were highly expressed while OSBPL6 was lowly expressed in liver cancer samples compared with normal samples." (PMID 36918840, 2023).
breast carcinoma (2 papers, 2019 to 2023). "Additionally, we found genes highly expressed in breast cancer stroma in the Human Protein Atlas (EGR1, OSBPL8, FAM171A2, FGD6, and CEP131), or likely expressed in fibroblasts (MMP13), that are reported to play a role in breast cancer progression among the most important ones." (PMID 31505876, 2019).
Hepatic steatosis (1 paper, 2025). Steatosis is a term used to denote lipid accumulation within hepatocytes. "Our in vitro and in vivo results supported the lipogenic role of Osbpl8 in relieving hepatic steatosis via the IRE1-XBP1 axis." (PMID 40448016, 2025). "We demonstrated that Osbpl8 is involved in relieving hepatic steatosis via the IRE1-XBP1 axis." (PMID 40448016, 2025).
lung carcinoma (1 paper, 2021). "Further evidence indicated that miR-421 is overexpressed in lung cancer cells and targets OSBPL8, suggesting that miR-421 can act as an anoikis repressor in lung cancer." (PMID 33435156, 2021). "In lung cancer, the overexpression of OSBPL8 hinders anchorage-independent growth." (PMID 33435156, 2021).
steatosis (1 paper, 2025). Increased lipid within the cytoplasm of cells. "Furthermore, Osbpl8 clearly reduced triglyceride accumulation, increased alanine transaminase (ALT) and aspartate transaminase (AST) levels, accelerated ATP generation, and attenuated steatosis, inflammation and oxidative stress." (PMID 40448016, 2025).
cancer (8 papers, 2016 to 2024). A tumor composed of atypical neoplastic, often pleomorphic cells that invade other tissues. "Oxysterol binding protein-like 8 (OSBPL8, also known as ORP8) triggers apoptosis induction by releasing cytochrome c from mitochondria and sensitizes cancer cells to Fas-mediated cell death." (PMID 33435156, 2021).
infection (2 papers, 2019 to 2024). The state of being infected such as from the introduction of a foreign agent such as serum, vaccine, antigenic substance or organism. "The significantly downregulated genes (NEAT1, TPM3, ZNHBA, CKLF, and OSBPL8) and the upregulated genes (ITMZC, IFNG, CD69, DNAJB9, and LYST) in NCAM1+FCGR3A+dNK cells after infection were also analyzed." (PMID 38730500, 2024).
tumor (2 papers, 2019). "EGR1, OSBPL8 (encoded by the gene KIAA1451), FAM171A2, FGD6, and CEP131 showed particularly high or largely exclusive staining in stromal cells, supporting the notion that indeed the expression profile of CAFs drives tumor classification in our random forest model." (PMID 31505876, 2019).
OSBPL8 also shares sentences with these, for which no sentence is quoted: atherosclerosis (3 papers); diabetes (3); colon cancer (2); colorectal cancer (2); cardiac insufficiency (1); cardiomyopathy (1); inflammatory bowel disease (1); myotonic dystrophy type 1 (1); Neurological Disorder (1); type 2 diabetes mellitus (1); uterine cancer (1).